E2F2 (E2F transcription factor 2)
Diseases named in the same sentence as E2F2 in open-access papers (continued):
Sharing a sentence is not in itself a finding about the gene and the disease.
rheumatoid arthritis (7 papers, 2018 to 2025). A chronic, systemic autoimmune disorder characterized by inflammation in the synovial membranes and articular surfaces. "E2F2 is overexpressed in rheumatoid arthritis synovial tissues indicating a possible association between E2F2 and rheumatoid arthritis." (PMID 33530456, 2021). "SiRNA-mediated knockdown of E2F2 attenuates the expression of inflammatory cytokines in rheumatoid arthritis synovial fibroblasts." (PMID 37293258, 2023). "IL-6, TNF-α and LPS stimulate the expression of E2F2 in rheumatoid arthritis synovial fibroblasts via NF-κΒ, ERK and STAT3 pathway." (PMID 33530456, 2021). "This study aimed to elucidate this mechanism and confirm the pathological roles of E2F2 in rheumatoid arthritis (RA)." (PMID 30286793, 2018). "E2F2 directly regulates the STAT1 and PI3K/AKT/NF-κB pathways to exacerbate the inflammatory phenotype in rheumatoid arthritis synovial fibroblasts and mouse embryonic fibroblasts." (PMID 40508152, 2025). "It has been shown that E2F2 upregulates IL-1 and TNF-a in rheumatoid arthritis (RA) synovial fibroblasts." (PMID 34198899, 2021). "As an apparent increase of E2F2 has been observed by researchers in rheumatoid arthritis (RA) synovial tissues, thus, it can be speculated that p16INK4a and E2F2 may participate in the progression of OA." (PMID 30219053, 2018). "Expression of E2F transcription factor 2 (E2F2), a transcription factor related to the cell cycle, is abnormally high in rheumatoid arthritis synovial fibroblasts (RASFs)." (PMID 30286793, 2018).
liver cancer (6 papers, 2016 to 2022). An epithelial or non-epithelial malignant neoplasm that arises from the liver. "Taken together, we demonstrate that targeting epigenetic reader by small molecule will be a good therapeutic strategy in liver cancer with underlying E2F2 down-regulation." (PMID 27081696, 2016). "On the basis of the microarray data, qRT–PCR and western blotting analysis were performed to confirm whether E2F2 was ANCCA/PRO2000-associated gene in liver cancer cells." (PMID 27239961, 2016). "Taken together, the results demonstrate that E2F2 is a direct target of the epigenetic reader BRD4 in liver cancer cells." (PMID 27081696, 2016). "Serial gene expression analyses with SK-Hep1 liver cancer cells treated with JQ1 to delineate the key player of BRD4 inhibition identified E2F2 as the first line of downstream direct target of BRD4." (PMID 27081696, 2016). "Taken together, we found that over-expression of epigenetic reader BRD4 in liver cancer and for the first time demonstrate that the BET protein inhibitor suppresses E2F2 itself and its downstream cell cycle regulation circuit in liver cancer." (PMID 27081696, 2016). "Taken together, these data suggest that E2F2 identified by BRD4 inhibition is a novel target for control of cell cycle in liver cancer." (PMID 27081696, 2016). "Of note, Western blot analysis of HCC subset tissues showed that BRD4-E2F2-cell cycle regulation axis is overexpressed, highlighting critical role of E2F2 in liver cancer." (PMID 27081696, 2016). "To investigate the clinical significance of E2F2 in liver cancer, we analyzed its expression using the NCBI GEO data base (GSE25097, GSE36376 and GSE45436) and TCGA data set." (PMID 27081696, 2016). "Down-regulation of E2F2 was evident at a very early time point (3 h) and its suppression was also detected in Huh7 and HepG2 liver cancer cells." (PMID 27081696, 2016). "Lastly, over-expression of E2F2 was significantly associated with poor prognosis of patients with HCC, demonstrating that BRD4-E2F2-cell cycle regulation circuit is a novel target in liver cancer." (PMID 27081696, 2016). "Using serial expression microarray and loss of function experiments followed integrated mining, we revealed that E2F2 is the first-line target of BRD4 inhibition and a promising therapeutic target in liver cancer." (PMID 27081696, 2016). "BRD4 inhibition by JQ1 selectively repressed transcriptional networks induced by E2F2 not through MYC and inverts liver cancer related gene expression signature." (PMID 27081696, 2016).
osteosarcoma (6 papers, 2006 to 2022). A usually aggressive malignant bone-forming mesenchymal neoplasm, predominantly affecting adolescents and young adults. "As reported let-7ainhibited cell proliferation via targeting of E2F2 in osteosarcoma cells." (PMID 29050238, 2017). "This is consistent with the ability of Rb661W to induce a proliferative arrest via p27 in osteosarcoma cells, and with evidence that Rb661W may regulate E2F-responsive genes through an interaction with E2F2." (PMID 17163992, 2006). "Among these we analyzed CD133, N-Myc, CCND2, E2F1 and E2F2, Bcl-2 and IAP-2, since they are overexpressed in 3AB-OS cells and many of them were found to be frequently overexpressed in tissues of osteosarcoma patients." (PMID 25174983, 2014). "We tested compensation by other activator E2Fs and found that knocking down E2F1 alongside E2F3, but not E2F2, reduced UHRF1 expression in osteosarcoma." (PMID 36068209, 2022).
osteoarthritis (5 papers, 2018 to 2024). A noninflammatory degenerative joint disease occurring chiefly in older persons, characterized by degeneration of the articular cartilage, hypertrophy of bone at the margins and changes in the synovial membrane. "It has been reported that miR-125a-5p-abundant exosomes derived from mesenchymal stem cells suppress chondrocyte degeneration via targeting E2F2 in traumatic osteoarthritis." (PMID 35081873, 2022). "For example in osteoarthritis, high level of E2F2 mRNA was detected in the cartilages of the patients with OA." (PMID 34709978, 2021). "Besides, imblanced expressions of E2F2 in osteoarthritis suggests a deterioration in cartilage catabolism and abnormal anabolism of damaged cartilage." (PMID 34709978, 2021). "In this study, we revealed a negative correlation within mir-125a-5p and E2F2 in traumatic osteoarthritis patients’ cartilage as well as in our mice model." (PMID 34709978, 2021).
astrocytomas (4 papers, 2010 to 2021). "In CD133(+) cells isolated from human astrocytomas, the expression of E2F2 was found to be upregulated and associated with the transformation of human astrocytes." (PMID 34476219, 2021). "E2F2 is up-regulated in CD133(+) astrocytoma cells and was implicated in astrocyte transformation." (PMID 33804958, 2021). "Therefore, it was suggested that E2F2 be used as a therapeutic target for astrocytoma eradication." (PMID 34476219, 2021). "Similarly, upregulation of E2F2 was found in astrocytomas of different grades." (PMID 20418948, 2010).
Autoimmunity (4 papers, 2014 to 2023). The occurrence of an immune reaction against the organism's own cells or tissues. "Mutations in E2F2 in mice cause enhanced T lymphocyte proliferation, leading to the development of autoimmunity." (PMID 36782330, 2023). "It has been shown in mice that deficiency in E2F2 caused by gene targeting (E2F2−/−) significantly increased the population of self-reactive peripheral T cells, causing symptoms similar to severe autoimmunity." (PMID 25202354, 2014). "E2F2‐deficient T lymphocytes exhibit elevated T cell receptor‐induced proliferation, which may contribute to autoimmunity in E2F2‐deficient mice." (PMID 34741389, 2021). "It has been reported that Rb-mediated gene expression repression of E2F2 (transcription factor 2), by acting to tether Rb to specific E2F promoter sites, was crucial in T cells, and mutation of E2F2 in mice resulted in enhanced T lymphocyte proliferation leading to the development of autoimmunity." (PMID 28028462, 2016).
breast tumors (4 papers, 2014 to 2024). "Transcriptional regulation of E2F2 plays a crucial role in HER2 overexpression, the overexpression of HER2 in breast tumors is associated with bad prognosis." (PMID 38807594, 2024). "Several studies have shown that E2F2 is overexpressed in breast tumors compared to normal tissue." (PMID 38807594, 2024). "Also, E2F1, E2F2, E2F3, Mps1/TTK, BubR1, NDC80 (HEC1), Nek2, and Sgo1 significantly co-overexpress in breast tumors." (PMID 29100415, 2017). "Observations that E2F1, E2F2, and E2F3 correlate with relapse-free but not overall survival was confirmed by mining the METABRIC database, a database that encompasses over 2000 breast tumors, with cBioPortal." (PMID 29100415, 2017).
diabetes (4 papers, 2010 to 2022). "Alterations in glucose metabolism have been previously linked to the E2F/Rb pathway as demonstrated by double knock-out of E2F1/E2F2 which impaired insulin production and caused diabetes." (PMID 28085920, 2017). "This indicates that E2F2 expression is regulated by lncRNA XR_108954.2, which provides new significant insights for the mechanistic study of diabetes." (PMID 35257412, 2022). "Genetic ablation of Cdk4 activity, cyclin D2, or combined E2f1 and E2f2, results in defective maintenance of adult pancreatic β-cells, eventually resulting in severe diabetes." (PMID 20090907, 2010).
lung adenocarcinoma (4 papers, 2018 to 2026). A carcinoma that arises from the lung and is characterized by the presence of malignant glandular epithelial cells. "constructed an E2F2-centered co-expression network and identified several key modules and networks overrepresented in Lung adenocarcinoma." (PMID 38807594, 2024). "In Selamat’s dataset, the mRNA expression of E2F2 in lung adenocarcinoma increases with a fold change of 2.238 (p < 0.005)." (PMID 29754146, 2018). "The results indicated that the expression levels of E2F1, E2F2, E2F3, E2F5, E2F6, E2F7, and E2F8 were higher in lung adenocarcinoma and squamous cell lung carcinoma tissues than in lung tissues, whereas and the expression level of E2F4 was lower in the former than in the latter." (PMID 29754146, 2018).
lymph node metastasis (4 papers, 2016 to 2020). "Similar to that found for E2F1, upregulated expression of E2F2 was also significantly associated with histological grade (p = 0.003), lymph node metastasis (p = 0.004), lymph vessel invasion (p = 0.014), and invasion depth of cervical stroma (p = 0.002)." (PMID 33061852, 2020). "Our study revealed that high E2F2 expression was closely related to the worse histologic grade, advanced clinical stage, more lymph node metastasis, and higher serum AFP value." (PMID 33115417, 2020).
Oral Squamous Cell Carcinoma (4 papers, 2021 to 2023). "Previous RNA sequence analysis (GSE134835) revealed E2F2 was significantly reduced by Zinc-finger protein 750 (ZNF750) in oral squamous cell carcinoma (OSCC)." (PMID 35003347, 2021). "The aim of this study was to evaluate E2F2, MDM2 and p16 concentrations in the tumour and margin samples of oral squamous cell carcinoma and to assess their association with some selected sociodemographic and clinicopathological characteristics of the patients." (PMID 37185737, 2023).
oropharyngeal squamous cell carcinoma (4 papers, 2021 to 2023). "Li and others documented that E2F2 variants are predictive biomarkers for recurrence risk in patients with OPSCC (oropharyngeal squamous cell carcinoma)." (PMID 36551770, 2022).
renal cell carcinoma (4 papers, 2017 to 2023). "In addition, reduced E2F2 concentrations were observed in renal cell carcinoma, which was associated with decreased cell proliferation and invasion." (PMID 37185737, 2023). "Taken together, our findings suggested that lncRNA RCAT1 could enhance the malignant phenotype of renal cell carcinoma cells by modulating miR‐214‐5p/E2F2 axis, and lncRNA RCAT1 might be a novel prognostic biomarker and a potential therapeutic target for renal cell carcinoma." (PMID 34244473, 2021).
Arthritis (3 papers, 2018 to 2023). Inflammation of a joint. "Indeed, NF-kB associates with the promoter region of E2F2, and activated E2F2 subsequently binds to the promoter of IL-6, which in turn leads to the development of arthritis." (PMID 37293258, 2023). "In RASFs, activated NF-κB can bind to the promoter region of E2F2, and activated E2F2 can bind to the promoter of IL-6 which, in turn, can promote the progression of arthritis." (PMID 30286793, 2018). "The occurrence and severity of collagen-induced arthritis were decreased in E2f2-KO mice compared with WT mice." (PMID 30286793, 2018). "Meanwhile, the severity of arthritis in WT mice 20 days after the second immunization was significantly higher than in E2f2−/− mice." (PMID 30286793, 2018). "Considering that arthritis and arthralgia are based on a complex inflammatory process, CDK4/6 inhibitors may attenuate E2F2 activity in synovium and cartilage and reverse, at least in part, the inflammation caused by aromatase inhibitors." (PMID 33530456, 2021).
cervical cancer (3 papers, 2020 to 2023). A primary or metastatic malignant neoplasm involving the cervix. "Considering that E2F2 and E2F7 downregulation inhibits proliferation of cervical cancer cells, we performed cell cycle analysis to evaluate the role of E2F2 and E2F7 in cell-cycle distribution." (PMID 33061852, 2020). "Similarly, we found that E2F2 mRNA expression levels were significantly increased by 2.190 times in cervical cancer tissues in the Biewenga Cervix dataset (p = 5.83E−6)." (PMID 33061852, 2020). "E2F2 and E2F7 are involved in cell proliferation, migration, and cell cycle in both HPV-positive and HPV-negative cervical cancer cells." (PMID 33061852, 2020). "Next, the inhibitory effect of E2F2 and E2F7 knockdown on cervical cancer cell growth was validated by CCK-8 analysis." (PMID 33061852, 2020). "We found that expression of E2F2 (p < 0.05) and E2F7 (p < 0.01) was significantly upregulated in primary cervical cancer tissues compared with adjacent normal tissues." (PMID 33061852, 2020). "Our findings showed that E2F2 and E2F7 knockdown induced cell cycle arrest in the G0/G1 phase in cervical cancer cells." (PMID 33061852, 2020). "Finally, in vitro experiments showed that E2F2 and E2F7 are involved in cell proliferation and migration and cell cycle regulation in both HPV-positive and HPV-negative cervical cancer cells." (PMID 33061852, 2020). "Expression levels of E2F2 and E2F7 in cervical cancer tissues were determined by RT-qPCR." (PMID 33061852, 2020). "We then confirmed these findings using IHC and RT-qPCR at the protein and mRNA level, and using in vitro experiments, showed that E2F2 and E2F7 are involved in cell proliferation, migration, and cell cycle regulation in both HPV-positive and HPV-negative cervical cancer cells." (PMID 33061852, 2020). "The association between CDKN2A expression and HPV infection in oral and cervical cancer demonstrated that HPV acts via the oncoprotein E7, which can bind the Rb protein, resulting in the inhibition of the formation of the Rb complex with E2F family of transcription factors (for example E2F2)." (PMID 36551770, 2022). "Thus, E2F2 and E2F7 promote cervical cancer cell proliferation through regulating the cell cycle." (PMID 33061852, 2020).
mesothelioma (3 papers, 2016 to 2023). A usually malignant and aggressive neoplasm of the mesothelium which is often associated with exposure to asbestos. "In a previous study we demonstrated a strong positive correlation between calretinin mRNA and protein levels in mesothelioma cell lines and demonstrated NRF-1 and E2F2 to act as transcription factors regulating calretinin expression." (PMID 28611824, 2017). "In the present study we found cis-regulatory sequence elements that are essential for calretinin expression in mesothelioma cells, and identified NRF-1/E2F2 as transcription factors binding to this regulatory sequence." (PMID 26848772, 2016). "A strongly reduced activity of the E2F2/NRF-1 mutant construct was also observed in HEK293 cells, indicating that this transcriptional control is not restricted to mesothelioma cells, but possibly to other cells of mesodermal origin." (PMID 26848772, 2016).
renal carcinoma (3 papers, 2016 to 2021). A carcinoma arising from the epithelium of the renal parenchyma or the renal pelvis. "Based on TCGA and GEO databases, the expression of E2F2 was significantly higher in renal cancer tissues compared to normal tissues." (PMID 34244473, 2021). "Besides, miR-155-5p is revealed capable of increasing the proliferation and invasion of renal cancer cells by targeting E2F2." (PMID 32587662, 2020). "The E2F2 expression was upregulated in renal cancer tissues with metastasis compared to those without metastasis." (PMID 34244473, 2021).
Sepsis (3 papers, 2025 to 2026). Sepsis is defined as life-threatening organ dysfunction caused by a dysregulated host response to infection. "Integrating WGCNA with three machine learning algorithms, we identified six diagnostic genes—PGM3, GDF15, GART, GFOD2, E2F2, and ATP1B2—associated with sepsis-induced ALI, which were validated in clinical samples by Western blotting." (PMID 41142807, 2025). "In addition, TTN-AS1 was proven to attenuate sepsis-induced myocardial injury via modulation of the miR-29a/E2F2 axis." (PMID 41602333, 2026). "SRSF7, E2F2, RAB13, and S100A8 were identified as potential pathogenic biomarkers of sepsis." (PMID 40909263, 2025). "E2F2 is a member of the E2F family the E2F family can regulate the cell cycle and mediate the functions of tumor suppressor proteins, and E2F2 expression has been identified as a potential diagnostic marker for ARDS secondary to sepsis." (PMID 40909263, 2025). "Similarly, recent evidence indicates that E2F2 may also participate in sepsis-related tissue protection by promoting M2 macrophage polarization and suppressing NF-κB signaling." (PMID 41142807, 2025). "RT-qPCR revealed decreased SRSF7 expression and increased RAB13, E2F2, and S100A8 expression in sepsis." (PMID 40909263, 2025). "The PBMC were separated of twenty patients with sepsis and twenty healthy volunteers, we estimated the mRNA expression level of SRSF7, E2F2, RAB13 and S100A8 in PBMC via RT-qPCR, the mRNA expression level of SRSF7(p<0.0001) was lower in the patients with sepsis than healthy people." (PMID 40909263, 2025).
squamous cell carcinoma (3 papers, 2017 to 2023). A carcinoma arising from squamous epithelial cells. "E2F2 and EMR2 expression was observed predominantly in the patients with adenocarcinoma rather than with squamous cell carcinoma." (PMID 29072692, 2017).
systemic lupus erythematosus (3 papers, 2016 to 2026). An autoimmune multi-organ disease typically associated with vasculopathy and autoantibody production.
thymoma (3 papers, 2007 to 2015). A neoplasm arising from the epithelial cells of the thymus. "In addition, overexpression of E2F2, which is a E2F member and downstream target of Rb, alters cell cycle progression in transgenic mice, causing a high incidence of thymomas." (PMID 26101855, 2015). "In an Eμ-pp-E2F2 mouse model, overexpression of E2F2 induced mild hyperplasia of the thymus in young mice and subsequent development of thymomas." (PMID 25202354, 2014).
bladder tumor (2 papers, 2010 to 2019). "In the present study, we demonstrated significantly higher expression of both E2F1 and E2F2 in bladder tumor tissues than in non-neoplastic tissues, which are probably due to aberrant transcriptional regulation of KDM5B." (PMID 20226085, 2010).
brain trauma (2 papers, 2018). "E2F2 and E2F3 were sensitized to neuronal cell loss after brain trauma." (PMID 30627556, 2018).
brain tumor (2 papers, 2014 to 2021). "Mice bearing orthotopic U87MG tumors also revealed differences in brain tumor development due to E2F2 knockdown." (PMID 25202354, 2014). "In agreement with the previous subcutaneous xenograft model, brain tumors derived from the stereotaxic intracerebral injection of U87MG cells with E2F2 knockdown were somewhat smaller than tumors derived from control cells, 30 days following injection in nude mice." (PMID 25202354, 2014).